MYO15B (myosin XVB)
Synonyms: MYO15BP
Tractability: PROTAC: its protein half-life has been measured.
Gene: Protein-coding gene on chromosome 17 (75,587,800 to 75,626,849, forward strand). Ensembl gene ENSG00000266714.
Subcellular location: Cytoplasm
Subcellular location (Human Protein Atlas): Cytosol
Gene Ontology:
Molecular function: protein binding; ATP binding; cytoskeletal motor activity
Cellular component: brush border; cytoplasm; cytoskeleton; myosin complex; plasma membrane bounded cell projection
Homologues: Orthologues: chimpanzee MYO15B (92% identical), rat Myo15b (66% identical), pig MYO15B (66% identical), mouse Myo15b (66% identical), macaque MYO15B (45% identical), tropical clawed frog myo15b (39% identical), zebrafish myo15b (20% identical).
Diseases named in the same sentence as MYO15B in open-access papers:
MYO15B is named in the same sentence as 8 diseases in open-access papers, as found by Europe PMC text mining. Sharing a sentence is not in itself a finding about the gene and the disease. The quoted sentences say what the papers report.
depressive disorder (3 papers, 2020 to 2023). A melancholy feeling of sadness and despair. "Chromosome 17q25.1, mapped by MYO15B, is associated with an increased risk of cognitive dysfunction, dementia, and depression." (PMID 37140907, 2023). "MYO15B genetic variants were found to be associated with an increased risk of depressive disorder in females, and the function of the protein is unknown, since it lacks a motor domain according to the GeneCards database." (PMID 36900421, 2023). "The study identified five genetic markers for increased risk of depression in women, three of which were rs201432982 for PDE4A, rs62640397, and rs79442975 for FDX1L, and the remaining two were rs820182 and rs820148 for MYO15B." (PMID 37140907, 2023).
breast carcinoma (2 papers, 2023 to 2024). "As a result, the combined model for TN breast cancer (TMEM132D, TMEM132C, MYO15B, S) demonstrated statistical significance (p = 0.0004) vs. the epigenetic model (TMEM132D, TMEM132C, MYO15B)." (PMID 36900421, 2023). "For TN breast cancer, the inclusion of the clinical stage in the epigenetic classifier made it possible to achieve an area under the curve cvAUC = 0.87; 95% CI = 0.86–0.88 with a sensitivity of 0.71 and a specificity of 0.80 for the “TMEM132D, TMEM132C, MYO15B, S” panel." (PMID 36900421, 2023).
colitis (1 paper, 2022). Inflammation of the colon. "ScRNA-seq analysis of colon and colitis showed that embryonic-specific genes reappear in response to intestinal damage, which is conserved both in human IBD and mouse DSS-induced colitis, including MYO15B, S100A11, and CDV3." (PMID 36045190, 2022).
viral infection (1 paper, 2020). "The functions of SPARC/Osteonectin, Cwcv and Kazal-like Domains Proteoglycan 1 (SPOCK1), Zinc Finger and BTB Domain Containing 11 (ZBTB11), and myosin XVB (MYO15B) in viral infection are unclear." (PMID 32223537, 2020).
MYO15B also shares sentences with these, for which no sentence is quoted: depression (2 papers); dementia (1); malignant neoplasms (1); Sepsis (1).